ADIPOR2 (adiponectin receptor 2)
Diseases named in the same sentence as ADIPOR2 in open-access papers (continued):
Sharing a sentence is not in itself a finding about the gene and the disease.
nasopharyngeal carcinoma (1 paper, 2022). A carcinoma arising from the nasopharyngeal epithelium. "We further determined if boosting the activity of both adiponectin receptors, AdipoR1 and AdipoR2, will stall the growth of nasopharyngeal carcinoma, if so, what is the impact of altering AdipoRs signaling on cell cycle progression of NPC cells." (PMID 35164782, 2022).
osteosarcoma (1 paper, 2020). A usually aggressive malignant bone-forming mesenchymal neoplasm, predominantly affecting adolescents and young adults. "In detail, we detected in Saos-2 and U2OS human osteosarcoma cell lines mRNA and protein expression levels of both canonical adiponectin receptors (ADIPOR1 and ADIPOR2) and noncanonical adiponectin receptor (CAD13)." (PMID 32411241, 2020).
papillary thyroid carcinoma (1 paper, 2021). "Indeed, Mitsiades reported that tissues and cell lines derived from human papillary thyroid carcinoma expressed Acrp30 receptors (AdipoR1 and AdipoR2)." (PMID 33587254, 2021).
pulmonary fibrosis (1 paper, 2015). Chronic progressive interstitial lung disorder characterized by the replacement of the lung tissue by connective tissue, leading to progressive dyspnea, respiratory failure, or right heart failure. "To test our hypothesis APN influences pulmonary fibrosis directly via lung fibroblasts, we confirmed the presence of AdipoR1 and AdipoR2 (the two known transmembrane APN receptors) in human lung fibroblasts WI-38 via Western and RT-PCR." (PMID 25945502, 2015).
scleroderma (1 paper, 2012). Scleroderma is a rare autoimmune connective tissue disorder characterized by abnormal hardening of the skin and, sometimes, other organs. "AdipoR2 levels were comparable in scleroderma and control fibroblasts." (PMID 23092446, 2012).
Sepsis (1 paper, 2025). Sepsis is defined as life-threatening organ dysfunction caused by a dysregulated host response to infection. "AdipoR2, predominantly expressed in hepatocytes and adipocytes, plays a metabolic role in sepsis by regulating lipid metabolism and energy homeostasis." (PMID 40652274, 2025).
Vertigo (1 paper, 2025). An abnormal sensation of spinning while the body is actually stationary. "By serving as a molecular sponge for miR-16-5p, it activates adiponectin receptor 2 (AdipoR2) and the PPARγ signaling pathway, significantly alleviating neuroinflammation, vertigo, neurological deficits, and apoptosis in MCAO mice." (PMID 41000399, 2025).
ZIKV infection (1 paper, 2023). "Although AdipoR1 and AdipoR2, the main receptors for adiponectin, are known to be ubiquitously expressed, we first ensured that it was the case in our A549 cell model of ZIKV infection." (PMID 38257725, 2023). "Hypothesizing that the cytoprotective action of AdipoRon could favorably influence the outcome of ZIKV infection, we found in our in vitro infection model of A549 cells expressing adiponectin receptors (mainly ADIPOR1 and to a lesser extent ADIPOR2) that AdipoRon was indeed able to limit infection." (PMID 38257725, 2023).
cancer (23 papers, 2011 to 2025). A tumor composed of atypical neoplastic, often pleomorphic cells that invade other tissues. "Associations between Adiponectin receptors (ADIPOR1 and ADIPOR2) and cancer characteristics are plotted using Least Square means (LS means)." (PMID 40642843, 2025). "In addition, adiponectin receptor 1 (AdipoR1) and adiponectin receptor 2 (AdipoR2), the main regulators of adiponectin, have been implicated in carcinogenesis in several cancers, including RCC." (PMID 28178338, 2017). "Intriguingly, the adiponectin receptors, ADIPOR1 and ADIPOR2 demonstrated opposing correlations with cancer characteristics such as grade, histology, LVSI, and microcystic elongated and fragmented (MELF) pattern." (PMID 40642843, 2025). "Conversely, the same cancer tissue exhibited lower expression of ADIPOR2 than the same benign control endometrium." (PMID 40642843, 2025). "In contrast, ADIPOR1 was mildly over‐expressed in the cancer tissue, whereas ADIPOR2 showed similar expression to the control sample." (PMID 40642843, 2025). "determined that AdipoR1 was expressed in 27% of primary malignant tumors, while AdipoR2 was found in 47% of primary malignant tumors via immunohistochemical staining of 49 thyroid tumor samples and metastatic lymph nodes." (PMID 38800384, 2024). "Other alterations in the ApN signalling cascade were observed, notably an increased AdipoR1 expression and a decreased AdipoR2 expression in the liver of cancer mice." (PMID 38572511, 2024). "In summary, ADIPOR1 and ADIPOR2 display the capacity to influence anti-cancer immunity and play vital roles in numerous tumors." (PMID 36896172, 2023). "To investigate the functions of ADIPOR1 and ADIPOR2 genes in tumors, we carried out a thorough pan-cancer analysis." (PMID 36896172, 2023). "Although we conducted a comprehensive analysis for the diverse roles of ADIPOR1 and ADIPOR2 across cancers, further experimental evidences are required to identify our results." (PMID 36896172, 2023). "Our study revealed that both ADIPOR1 and ADIPOR2 were positively associated with CD4+ T cell and negatively associated with NK cell in most cancers." (PMID 36896172, 2023). "CD274, encoding PD-L1, was observed significantly correlated with ADIPOR1 and ADIPOR2 in almost all the cancers." (PMID 36896172, 2023). "Both ADIPOR1 and ADIPOR2 exhibited correlations with diverse immune checkpoint genes in various cancers." (PMID 36896172, 2023). "ADIPOR1 and ADIPOR2 were correlated with stemness in many cancers, even though they only had weak correlations with TMB and MSI." (PMID 36896172, 2023). "Both ADIPOR1 and ADIPOR2 genes are dysregulated in most cancers, but their genomic alteration frequencies are low." (PMID 36896172, 2023). "ADIPOR1 was predominantly upregulated in cancers, whereas ADIPOR2 was downregulated in many cancers." (PMID 36896172, 2023). "According to the GSE44076 dataset analysis, ADIPOR1 mRNA levels were increased in primary tumors when compared to adjacent normal colon mucosa, while ADIPOR2 mRNA levels were decreased in cancer (p < 0.0001)." (PMID 36429712, 2022). "Accumulating evidence has shown that the expression of AdipoRs (AdipoR1 and AdipoR2) can be observed in human cancer tissues." (PMID 33752745, 2021). "Most of the biological effects of Acrp30 are mediated by its receptors, AdipoR1 and AdipoR2, which belong to the seven-transmembrane-domain receptor family and have been shown to have abnormal expression in various types of human cancer." (PMID 33752745, 2021). "This is followed by CFTR (18 cancer types) and four other genes that were amplified in 17 cancer types (ADIPOR2, LEP, PRKAG2 and RHEB)." (PMID 32807122, 2020). "Immunohistochemical analysis of human and murine PDAC tumors showed a downregulation of both adiponectin receptors, ADIPOR1 and ADIPOR2, in cancer compared to adjacent normal acinar tissue." (PMID 29156726, 2017).
cancer (continued). "Consequently, a total of 11 studies were enrolled in the meta-analysis investigating the relationships between LEP/LEPR/ADIPOQ/ADIPOR1/ADIPOR2 variants and total PCa risk, and ten studies were included in the pooled-review discussing these polymorphisms' impact on the aggressiveness of cancer." (PMID 27768592, 2016). "Circulating adiponectin levels are influenced primarily by the activity of adiponectin receptors 1 and 2 (ADIPOR1, ADIPOR2), and some studies have linked ADIPOR1 dysfunction with development of cancer." (PMID 26047008, 2015). "Adiponectin is a mammalian hormone that exerts anti-diabetic, anti-cancer and cardioprotective effects through interaction with its major ubiquitously expressed plasma membrane localized receptors, AdipoR1 and AdipoR2." (PMID 23762377, 2013). "Dose-dependent effects of ADP 355 were tested in different cancer cells lines expressing AdipoR1 and AdipoR2." (PMID 21974986, 2011). "AdipoR1 and AdipoR2 were positively detected in the cytoplasm as well as the cell membrane of cancer cells." (PMID 22078265, 2011). "Notably, ADIPOR1 and ADIPOR2 showed opposite correlations with cancer traits like grade, histology, and LVSI." (PMID 40642843, 2025). "We conducted a comprehensive pan-cancer analysis for the roles of AdipoR1 and AdipoR2 via several public databases, including expression differences, prognostic value, and the correlations with tumor microenvironment, epigenetic modification, and drug sensitivity." (PMID 36896172, 2023). "ADIPOR1 and ADIPOR2 exhibited a wide positive correlation across cancers." (PMID 36896172, 2023). "Some studies have focused on how ADIPOR1 and ADIPOR2 affect cancer prognosis." (PMID 36896172, 2023). "Low genetic alteration frequency was seen for both ADIPOR1 and ADIPOR2 across cancers." (PMID 36896172, 2023). "Hence, using a number of public databases, we carried out this study to explore the roles of ADIPOR1 and ADIPOR2 across cancers." (PMID 36896172, 2023). "The proliferation of these AdipoR2-treated cancer cells was then assessed using WST-8 assays." (PMID 33752745, 2021). "Additionally, ADIPOR2 exhibited a positive correlation with endothelial cells in many cancers." (PMID 36896172, 2023). "In addition, both the ADIPOR1 and ADIPOR2 exhibited extensive correlations with immune checkpoint genes in the majority of cancers, indicating that they may be used as predictors or novel targets of immunotherapy." (PMID 36896172, 2023). "Hence, there is an urgent need to explore the roles of AdipoR1 and AdipoR2 in cancers." (PMID 36896172, 2023). "ADIPOR1 and ADIPOR2 play critical roles in diverse cancers, and it is a potential strategy to treat tumors through targeting ADIPOR1 and ADIPOR2." (PMID 36896172, 2023). "Although they possessed significant correlations across cancers, the expression patterns of ADIPOR1 and ADIPOR2 were varied." (PMID 36896172, 2023). "In order to adequately address ADIPOQ’s numerous roles in cancer and immunity, the research focus has shifted toward its receptors: ADIPOR1, ADIPOR2 and T-cadherin." (PMID 36429712, 2022). "ADIPOR1 was mildly overexpressed in cancer tissue, suggesting a role in the altered metabolic signaling in the tumor, while ADIPOR2 remained unchanged, possibly indicating a more stable or non‐dominant role in this context." (PMID 40642843, 2025). "In addition to human orthologs previously identified as playing key roles in OSCC, p63 signaling, and other cancers, namely, FAT2, K14, and PERP, we identified several novel regulators, including Cotl1, Bcam, Adipor2, and Wnt7b." (PMID 36672394, 2023). "Although the expression of AdipoR1 and AdipoR2 was previously observed in human cancer tissues, there are no clear indications about the presence of these receptors in human brain tumours." (PMID 33752745, 2021). "However, the mechanisms through which AdipoR2 affects cancer cells have not been completely elucidated." (PMID 33752745, 2021).
tumor (21 papers, 2009 to 2025). "AdipoR2, which belongs to the seven-transmembrane-domain receptor family, has been shown to play an important role in the development of human tumours, but the underlying mechanisms are poorly understood." (PMID 33752745, 2021). "The inhibitory effect of AdipoRon on tumor growth was significantly attenuated when AdipoR2 and ULK1 were silenced." (PMID 39349421, 2024). "In summary, our findings provided evidence for the positive regulation of AdipoR1 and AdipoR2 in tumor proliferation and invasion in vitro and demonstrated an association between AdipoR1/2 and poor survival in both IHC samples and public datasets." (PMID 37454080, 2023). "By contrast, ADIPOR2 mRNA levels in tumor-adjacent mucosa were equivalent to the levels in healthy cells while being decreased in tumors." (PMID 36429712, 2022). "PDAC samples collected from a genetically engineered mouse (GEM), PKT (Ptf1acre/+; KrasG12D/+; Tgfbr2fl/fl), also showed a decrease of both ADIPOR1 and ADIPOR2 in tumor tissue compared to the adjacent normal acinar tissue." (PMID 29156726, 2017). "Consistent with a previous study, the AdipoR1 and AdipoR2 expression levels significantly decreased in tumor tissues compared with surrounding normal parenchyma tissue." (PMID 28178338, 2017). "As further examples, the Ago-IP enriched mRNAs ATM interactor (ATMIN), considered to be a tumor suppressor, and the adiponectin receptor 2 (ADIPOR2), a known inhibitor of proliferation, are both potential targets for the upregulated miR-200c." (PMID 28163933, 2017). "Yet, in a single-cohort study of patients affected by PTC, tumor expression of adiponectin receptors (both AdipoR1 and AdipoR2) was positively correlated with the tumor aggressiveness." (PMID 29184536, 2017). "While the presence of both ADIPOR1 and ADIPOR2 has previously been reported in human PDAC tumor samples, the localization and the expression level of these receptors relative to normal tissue has not been investigated." (PMID 29156726, 2017). "One group presented a positive correlation with T category and TNM stage, whereas other investigators showed AdipoR2 to be inversely related to T category, N category, tumor stage and lymphovascular invasion." (PMID 26931562, 2016). "When determining intensity alone adiponectin, PGF2α, F2-isoprostanes levels were higher in the tissues adjacent to the tumor than the tumor tissue whereas AdipoR2, leptin, and COX-2 levels were higher in the tumor tissues." (PMID 26431176, 2015). "The tumor‐suppressive effects of adiponectin are largely mediated through its receptors, adiponectin receptor 1 and adiponectin receptor 2 (AdipoR1 and AdipoR2), which activate key pathways, including AMPK and Peroxisome proliferator‐activated receptor alpha (PPAR‐α)." (PMID 40387523, 2025). "Additionally, our case–control study’s finding of downregulated ADIPOR1 gene expression and unaltered ADIPOR2 in PBMCs was equivalent to the transcriptional trend observed in tumor-adjacent mucosa." (PMID 36429712, 2022). "Thus, tumor cells seem to down-regulate their response to adiponectin by decreasing the expression of AdipoR2 in the cell membrane." (PMID 29212223, 2017). "Adiponectin may influence cancer risk through its well recognized effects on insulin resistance, but it is also plausible that it acts on tumor cells directly, because several tumor cell lines express AdipoR1 and AdipoR2." (PMID 20030801, 2009). "Our research revealed that ADIPOR1 and ADIPOR2 are dysregulated in a wide range of tumors, and that they play critical roles in anti-tumor immunity as well as drug sensitivity, which indicated that adipose tissues might affect tumor tissues via interacting with AdipoR1/2 receptors." (PMID 36896172, 2023). "The anti-tumor impact of DCs can be diminished by AdipoR1 activating the AMPK and MAPKp38 pathways and AdipoR2 initiating the COX-2 and PPAR pathways." (PMID 36896172, 2023).
tumor (continued). "Namely, when adjacent mucosa was compared to malignantly transformed mucosa, decreased ADIPOR2 mRNA and increased ADIPOR1 mRNA levels were demonstrated in tumor tissue." (PMID 36429712, 2022). "A decrease of AdipoR2 expression was found in 786-O and ACHN (tumor cells) incubated with hRATfT- and hRATnT-CMs vs. control-CMs (p<0.001)." (PMID 29212223, 2017). "To mimic the physiological and pathological states of human PTC, we established PTC tumor-bearing mouse models using PTC cell lines with NC (normal control), sh-AdipoR1 (AdipoR1 gene silencing), sh-AdipoR2 (AdipoR2 gene silencing), and sh-ULK1 (ULK1 gene silencing)." (PMID 39349421, 2024). "The GSEA analysis of the GSE44076 dataset showed that ADIPOR2 was positively correlated with metabolism-related gene sets, such as cholesterol homeostasis, glycolysis, steroid biosynthesis and the PPAR signaling pathway in tumor tissue." (PMID 36429712, 2022). "Additionally, our results show a decrease in AdipoR2 expression in 786-O and ACHN (tumor cells) incubated with hRATfT- and hRATnT-CMs vs. control-CMs." (PMID 29212223, 2017). "The correlations between AdipoR1 or AdipoR2 and tumor TNM stage or location were not significant (p > 0.10)." (PMID 26931562, 2016). "We additionally examined the differential expression of AdipoR1, AdipoR2, AGE, RAGE and GLO-I between mucinous and non-mucinous tumours." (PMID 26931562, 2016).
cardiovascular disease (9 papers, 2010 to 2022). "We have demonstrated for the first time that a sequence variant in the intron 5 of the ADIPOR2, rs767870 among the eight studied, is associated with cardiovascular disease in our population of Greek individuals." (PMID 20178558, 2010). "Thus, high ADIPOR2 levels may be associated with an increased risk of developing cardiovascular disease in humans." (PMID 24324556, 2013). "We chose to study ADIPOR2 because the effects of ADIPOR2 gene variants in cardiovascular disease have not yet been examined." (PMID 20178558, 2010).
infection (5 papers, 2023 to 2025). The state of being infected such as from the introduction of a foreign agent such as serum, vaccine, antigenic substance or organism. "Decreased AM transcription of Adipor1 and Adipor2 by infection was partially restored by AdipoRon treatment." (PMID 38979340, 2024). "To ascertain ZIKV’s ability to inhibit the adiponectin receptor expression, we infected A549 cells with ZIKVPF13 at different MOIs and monitored the effect on both ADIPOR1 and ADIPOR2 expression after 24 h of infection." (PMID 38257725, 2023). "We demonstrated ZIKV’s ability to halve the ADIPOR1 and ADIPOR2 expression as early as 24 h post-infection." (PMID 38257725, 2023). "In addition, for other cell organelles, peroxisome-related genes (Adipor1, Adipor2, Ppara), Cytochrome P450-related genes (Cyp2e1) and Cytochrome c-related genes (Cycs) were significantly lower in the inf + nisin group than the infection group." (PMID 38233485, 2024). "After infection, APN was significantly increased only in males, in individuals aged 65 years and above and in overweight individuals; AdipoR2 mRNA levels were higher in females and individuals under 65 years of age, but not significantly elevated across any BMI subgroups." (PMID 39840070, 2024).
metabolic disease (2 papers, 2023 to 2026). A congenital disorder (due to inherited enzyme abnormality) or acquired (due to failure of a metabolically important organ) disorder resulting from an abnormal metabolic process. "Adiponectin receptors, AdipoR1 and AdipoR2 are promising targets for the prevention and treatment of metabolic diseases." (PMID 37948516, 2023).
neurodegenerative disease (2 papers, 2021 to 2023). A disorder of the central nervous system characterized by gradual and progressive loss of neural tissue and neurologic function. "Importantly, all of these synaptic regulators (Nos1, Lrp8, Argef2, Sema5b) and other significantly altered splice variants (e.g., Adipor2, Mapk14, Smarca4, Sort1, Mapt) have been linked to AD and other neurodegenerative diseases." (PMID 37819053, 2023).
adenocarcinoma (1 paper, 2016). A common cancer characterized by the presence of malignant glandular cells. "Mucinous adenocarcinomas had marginally higher AdipoR1 and AdipoR2 expression levels (Mann–Whitney U test, p = 0.0739 and 0.0993)." (PMID 26931562, 2016).
colon polyp (1 paper, 2008). "We generated three types of gene-deficient mice (adiponectin-deficient, adiponectin receptor 1-deficient, and adiponectin receptor 2-deficient) and investigated chemical-induced colon polyp formation and cell proliferation in colon epithelium." (PMID 18676419, 2008).
colorectal (1 paper, 2016). "AGE and AdipoR1 are possibly involved in colorectal carcinogenesis, whereas AdipoR2 and GLO-I emerged as novel independent prognostic biomarkers of adverse significance for patients with early disease stage." (PMID 26931562, 2016).